TIMELESS (timeless circadian regulator)
Diseases named in the same sentence as TIMELESS in open-access papers (continued):
Sharing a sentence is not in itself a finding about the gene and the disease.
cancer (continued). "One previous study demonstrated that TIMELESS supports cancer cells by increasing MYC expression and activity." (PMID 30629587, 2019). "This and previous studies have demonstrated that TIMELESS is highly expressed in multiple types of cancer." (PMID 30629587, 2019). "This increase in TIMELESS expression promoted cancer cell proliferation as depletion of TIMELESS reduced the number of cell divisions due to cells undergoing G2/M arrest." (PMID 30629587, 2019). "In the control network, let-7e-5p is linked to miR-139-5p, a candidate tumor suppressor targeting TIMELESS and found down-regulated in many cancer types, but in the tumor network this important link was lost." (PMID 27323779, 2016). "We identified a cancer-relevant network of transcripts with altered expression following TIMELESS knockdown which contained many genes with known functions in cancer development and progression." (PMID 24161199, 2013). "Consequently, the objective of this study is to thoroughly analyze bioinformatic data to investigate the function of TIMELESS in multiple cancer types." (PMID 38053143, 2023). "In addition, it is yet unclear how TIMELESS affects the tumor immune microenvironment and what functions it plays in a particular form of cancer." (PMID 38053143, 2023). "Recent research has shown that TIMELESS plays an important role in cancer progression." (PMID 35715407, 2022). "Interestingly, overexpression of CLASPIN and TIMELESS protects cancer cells from replication stress making them promising anti‐cancer targets." (PMID 34694004, 2021). "In addition, it was shown that Cluster 1 (CRY2, PER1, and RORA) and TIMELESS exerted opposite impacts on interactive gene network, infiltration of immune cells, cancer-related signaling pathways, and cellular sensitivity to clinically used drugs." (PMID 34745328, 2021). "TIMELESS, first discovered in Drosophila, has been found in recent years to regulate various cellular functions, embryonic development, and initiation and progress of cancer, apart from regulating the circadian rhythm of organisms." (PMID 33430865, 2021). "Besides, CRY2, PER1, and RORA exerted opposite impacts against TIMELESS on immune cell infiltration and cancer-related signaling pathways, affecting the overall survival of HCC patients." (PMID 34745328, 2021). "Another report proposed that TIMELESS could support cancer by supporting Ras signaling as Ras mRNA expression was downregulated following TIMELESS depletion." (PMID 30629587, 2019). "The data show that ERK activation contributes to the overexpression of TIMELESS in cancer." (PMID 30629587, 2019). "Additionally, TIMELESS depletion slows cancer cell proliferation by inducing G2/M arrest as a result of DNA damage triggering inactivating phosphorylation of CDK1." (PMID 30629587, 2019). "TIMELESS is overexpressed in cancer and required for increased cancer cell proliferation." (PMID 30629587, 2019). "Primary or subgroup meta-analysis for the SNPs concerning all the other clock genes (ARNTL, CRY1, CSNK1E, NR1D1, TIMELESS) considered in this study were found to be not statistically significantly associated with cancer risk." (PMID 28177907, 2017). "We analyzed TIMELESS expression in OSCC using western blot, immunohistochemistry, qRT-PCR, and data from The Cancer Genome Atlas (TCGA) and the Cancer Cell Line Encyclopedia (CCLE)." (PMID 38178094, 2024). "Heterogeneous distribution of CRGs was observed in cancers: clock control genes such as HLF and RORs were lowly expressed in most tumors, while core clock genes such as TIMELESS and NPAS2 were highly expressed." (PMID 36895015, 2023). "As TIMELESS expression was significantly upregulated and RORA, PER1, PER2, and CRY2 expression was significantly downregulated in most cancer types including LUAD and LUSC, it is necessary to probe their prognostic values." (PMID 35078435, 2022).
cancer (continued). "TIMELESS (TIM), as a circadian clock gene, has been found to be highly expressed and predictive of poor prognosis in various cancers." (PMID 34490127, 2021). "Firstly, TIMELESS and TIPIN are co‐ordinately over‐expressed in many human cancer cells, where they are important to combat the inherent DNA replication stress that is a feature of the cancerous state." (PMID 34269473, 2021). "Among them, the expression of TIPIN, TIMELESS, ARNTL2, ARNTL, and AANAT are positively correlated with the infiltration level of tumor‐infiltrating lymphocytes in pan‐cancer, respectively." (PMID 31927791, 2020). "Downstream of γH2AX, all five cancer cell lines demonstrated increased phosphorylation of CHK1 and CDK1, which provides a mechanism for the G2/M arrest following TIMELESS depletion." (PMID 30629587, 2019). "While the connection between circadian rhythm disruption and cancer genesis is well-documented, the specific role of TIMELESS in the metabolic reprogramming of OSCC cells has not been thoroughly explored." (PMID 38178094, 2024). "We also carried out immunohistochemical labeling of the TIMELESS in numerous clinical tumor tissues and the HPA database to confirm the preceding conclusion that aberrant TIMELESS expression was substantially connected with poor prognosis in certain cancers." (PMID 38053143, 2023). "TIMELESS has been shown to be expressed in a circadian fashion in normal tissue; however, it is likely constitutively overexpressed in cancer due to its oncogene-driven expression." (PMID 30629587, 2019).
tumor (24 papers, 2012 to 2025). "Upon comparing mRNA expression levels of CRGs in tumor and normal tissues, it was observed that the expression of the TIMELESS gene was elevated and associated with poor prognosis, confirming findings from previous studies." (PMID 40191195, 2025). "Findings indicate that ncRNA mediate upregulation of TIMELESS, which is associated with tumor immune cell infiltration and poor prognosis in LUAD." (PMID 38261568, 2024). "The expression of TIMELESS and the association of TIMELESS with tumor immune cell infiltration and prognosis in LUAD remain to be elucidated." (PMID 38261568, 2024). "A total of 85 miRNAs with potential to interact with TIMELESS were identified in TCGA LUAD tumor tissues." (PMID 38261568, 2024). "Immunohistochemistry (IHC) in tumor tissues from nude mice also showed reduced SIRT1 expression upon TIMELESS knockdown." (PMID 38178094, 2024). "A heatmap of immune cell infiltration confirmed that increased TIMELESS expression was associated with CD4+ T and Th2 cell infiltration in TCGA LUAD tumor tissues." (PMID 38261568, 2024). "Comparative analysis between the control group and the TIMELESS knockdown group revealed a notable reduction in tumor size and weight in the latter, indicating that TIMELESS knockdown effectively inhibited tumor growth in the xenograft model." (PMID 38178094, 2024). "In the present study, TIMELESS expression was significantly negatively correlated with hsa-miR-1-3p expression in LUAD tumor tissues, and high hsa-miR-1-3p expression was significantly associated with improved OS in LUAD." (PMID 38261568, 2024). "Given its influence on tumor growth, TIMELESS emerges as a promising biomarker for OSCC diagnosis and a potential therapeutic target." (PMID 38178094, 2024). "In exploring the role of TIMELESS in cellular metabolism, we focused on its impact on glucose metabolism, a key aspect of tumor cell proliferation." (PMID 38178094, 2024). "For example, the circadian gene TIMELESS was found to be highly expressed in BC conditions, predicting a poor prognosis (e.g., tumor growth) after positive regulation of sphingolipid metabolism." (PMID 36012374, 2022). "TIMELESS is upregulated at the mRNA level in multiple tumor types compared to normal solid tissue (TCGA)." (PMID 30629587, 2019). "PER1, PER2, PER3, CRY2 were found to be significantly down-expressed, while CLOCK, TIMELESS were over-expressed in the studied tumor samples compared to the non-tumor samples." (PMID 29958276, 2018). "TIMELESS was found to be frequently overexpressed in different tumor types compared to normal controls." (PMID 24161199, 2013). "Additionally, our results extend this understanding by demonstrating that TIMELESS not only promotes OSCC cell proliferation but also contributes to tumor growth both in vitro and in vivo." (PMID 38178094, 2024). "TIMELESS might exert its oncogenic role by decreasing immune cell infiltration in the LUAD tumor microenvironment, and TIMELESS expression in LUAD tumor tissues may predict a poor response to immune checkpoint inhibitors." (PMID 38261568, 2024). "NcRNA analysis showed MIR4435-2HG/hsa-miR-1-3p may interact with TIMELESS in a competitive endogenous RNA network in LUAD tumor tissues." (PMID 38261568, 2024). "TIMELESS may be involved in carcinogenesis by modulating cell cycles, DNA repair, and tumor immunity." (PMID 38261568, 2024). "In addition, using immunohistochemistry (IHC), we confirmed the expression of TIMELESS in clinical patients across several tumor types." (PMID 38053143, 2023). "Knockdown of TIMELESS significantly slowed tumor growth in vivo." (PMID 37183243, 2023). "Interestingly, Superoxide dismutase (SOD2), a probable tumor suppressor responsible for the destruction of superoxide free radicals, displayed a 15.9-fold increase in expression following TIMELESS knockdown." (PMID 24161199, 2013).
tumor (continued). "Notably, high TIMELESS expression was associated with increased infiltration of activated CD4+ T cells and immunosuppressive Th2 cells and decreased infiltration of CD8+ T cells, cytotoxic Th1 cells, and dendritic cells in LUAD tumor tissues." (PMID 38261568, 2024). "MIR4435-2HG and hsa-miR-1-3p may interact with TIMELESS in a ceRNA network in LUAD tumor tissues." (PMID 38261568, 2024). "TIMELESS maybe the key gene related to tumor and immune and lipid metabolism." (PMID 35078435, 2022). "Indeed, CRY2, PER1, and RORA were downregulated, and TIMELESS was upregulated in tumor tissues, suggesting that TIMELESS may play a different role in HCC." (PMID 34745328, 2021). "In summary, RAD51, TIMELESS, RFC3, and TONSL converge on pro-proliferative pathways that sustain tumor survival and expansion." (PMID 41179682, 2025). "Intersection of these gene sets yielded four high-confidence tumor dependency genes (TONSL, TIMELESS, RFC3, RAD51) for further investigation." (PMID 41179682, 2025). "The role of TIMELESS in OSCC was examined through clone formation, MTS, cell cycle, and EdU assays, alongside subcutaneous tumor growth experiments in nude mice." (PMID 38178094, 2024). "TIMELESS was significantly upregulated (P < 0.05) while RORA was significantly downregulated (P < 0.0001) in tumor tissue compared to the adjacent normal tissue." (PMID 35078435, 2022). "Overall, our study identifies TONSL, TIMELESS, RFC3, and RAD51 as tumor dependency genes." (PMID 41179682, 2025). "Notably, TONSL, TIMELESS, RFC3, and RAD51 exhibited significantly higher expression levels within the tumor regions compared to the tumor stromal areas, suggesting their predominant role in tumor cells." (PMID 41179682, 2025). "Further, TIMELESS expression in LUAD tumor tissues was significantly negatively correlated with an immunophenoscore that predicted response to immune checkpoint inhibitors, reflecting the impact of TIMELESS on immune cell infiltration." (PMID 38261568, 2024). "It is noteworthy that there were no substantial differences in the overall body weight of the mice across the various treatment groups, suggesting the specificity of TIMELESS knockdown effects on tumor growth rather than general health." (PMID 38178094, 2024). "Moreover, using bioinformatics analysis, we probed the function of TIMELESS and RORA in multiple aspects, especially in tumor immune regulation and TIMELESS in lipid metabolism." (PMID 35078435, 2022). "Besides, the overlapping genes that exhibited similar expression levels in tumor samples from both the TCGA and ICGC databases were shown in a Venn diagram, including DBP, NPAS2, PER1, RORA, and TIMELESS." (PMID 34745328, 2021). "High expression of Cluster 1, or low expression of TIMELESS, might inhibit both the infiltration of B cells and nTreg cells, suggesting that the dysregulation of circadian clock genes may manifest HCC by disrupting the tumor microenvironment." (PMID 34745328, 2021). "TIMELESS expression at the mRNA and protein levels was evaluated in CaCo2, HCT116, HT29, SW480 and SW620 cells: TIMELESS mRNA expression was higher in tumor than non-tumor mucosa and mainly in CaCo2 and HT29 cells with respect to HCT116, SW480 and SW620 cells." (PMID 27323779, 2016).
TIMELESS also shares sentences with these, for which no sentence is quoted: breast tumor (2 papers); non-small cell lung carcinoma (2); alcohol abuse (1); antiphospholipid syndrome (1); asthma (1); autism (1); gastric cancer (1); hepatocellular carcinoma (1); insomnia (1); lymph node metastases (1); medulloblastoma (1); mental disorder (1); mood disorder (1); nasopharyngeal carcinoma (1); oral squamous cell carcinoma (1); rectal cancer (1); renal carcinoma (1); schizoaffective disorder (1); Sepsis (1); skin cutaneous melanoma (1); sleep disorder (1); thyroid cancer (1).